TERT (telomerase reverse transcriptase)
Diseases named in the same sentence as TERT in open-access papers (continued):
Sharing a sentence is not in itself a finding about the gene and the disease.
tumor (continued). "The analysis of tumor recurrence revealed that TERT amplification was a better predictor of tumor relapse than TPM, extrathyroidal extension, tumor multifocality or tumor size ≥ 5 cm, DMs at diagnosis, and stage at diagnosis I–II vs. III–IV." (PMID 40272676, 2025). "Overexpression of TERT has been observed in PCa, contributing to cellular immortality and tumor progression." (PMID 41402347, 2025). "A 2020 systematic analysis using 31 different tumor types from 6835 patients reported that TERT amplification is present within 4% of tumors." (PMID 39858038, 2025). "Mutational biomarkers also offer important insights; TERT promoter mutations and CDKN2A alterations have been associated with aggressive tumor features and shorter recurrence-free duration, but standardized clinical integration remains lacking." (PMID 40981345, 2025). "Molecular analysis of tumor tissue from patient P3 documented the TERT rearrangement breakpoint as well as the previously reported ALK p.R1275Q mutation." (PMID 39760332, 2025). "the BRAF-driven MAPK pathway can upregulate TERT promoter activity, while TERT cooperates with mutant BRAF to drive tumor dedifferentiation and progression through mechanisms such as the modulation of ribosomal biogenesis." (PMID 41306438, 2025). "Further evaluation of the tumor by Caris Molecular Intelligence revealed several mutations, including the NF1 variant of uncertain significance (VUS), NRAS, PBRM1, FAT1, TERT Promoter, and ATM." (PMID 40125165, 2025). "We also used Sanger sequencing to detect six genes—KRAS, NRAS, HRAS, TERT, RET, and BRAF—in the tumor tissue and identified a C228T mutation in the TERT promoter region." (PMID 41488090, 2025). "We also conducted univariate and multivariate analyses and found that tumor size and the presence of BRAF V600E and TERT promoter co-mutations were significant predictors of second recurrence." (PMID 40988283, 2025). "Our study takes the first crucial step toward addressing this gap by demonstrating that the proportion of TERT + leukocytes decreases significantly with tumor progression." (PMID 41417416, 2025). "To increase the sensitivity by simultaneously tracking multiple tumor mutations, we additionally included genes in the panel that are commonly altered in MLS, such as PIK3CA and the TERT promoter region." (PMID 39980272, 2025). "Ongoing clinical trials are exploring TERT as a potential immunotherapeutic target, particularly in combination with immune checkpoint inhibitors, to enhance RT efficacy in immunosuppressive tumor microenvironments." (PMID 41007699, 2025). "In human stem cells and approximately 85% of tumor cells, telomerase formed by TERT and TERC RNA complex is responsible for elongating telomeres." (PMID 40696438, 2025). "Mutations in the TERT promoter are commonly observed in DTC and are strongly associated with tumor dedifferentiation." (PMID 40927522, 2025). "TERT + leukocyte alterations occurred earlier than CTC detection and were closely associated with tumor invasion depth and patient outcomes." (PMID 41417416, 2025). "None of those studies has proved, however, a statistically significant correlation between TERT amplification and the patient’s tumor stage." (PMID 40272676, 2025). "Here, we demonstrated the presence of TERT inside the mitochondrion in different cellular contexts, both in tumor and normal cell lines and even under physiological conditions, differently from previous studies." (PMID 41144538, 2025). "Genetic events like mutations in PIK3CA, TERT alterations, and EGFR amplifications found in the primary tumor typically persist in the recurrent tumor." (PMID 40141375, 2025).
tumor (continued). "TERT-targeted therapeutic vaccines are designed to activate T cells that recognize specific tumor antigens, thus enhancing the immune response against cancer cells." (PMID 40227701, 2025). "This case highlights several unique characteristics: advanced patient age, tumor recurrence after GTR, and the presence of a TERT promoter mutation—the first reported instance in spinal CM." (PMID 41013491, 2025). "In B-cell malignancies, TERT also exhibits extratelomeric functions that impact several pathways sustaining autonomous cancer cell proliferation, resistance to apoptosis, and tumor progression." (PMID 40227701, 2025). "Meanwhile, few genes were uniquely expressed in TERT altered tumours; amongst these were IRX3, SDK1 and TRIP13." (PMID 40097403, 2025). "Through this interaction, TERT can create a pro-inflammatory environment that supports tumor growth and progression." (PMID 40243493, 2025). "These criteria include being younger and having a multifocal tumor with a potentially aggressive molecular phenotype, as indicated by the presence of BRAF and TERT mutations, as well as PD-L1 positivity." (PMID 40650194, 2025). "High glucose levels have been shown to epigenetically modulate TERT expression, increasing its transcription and promoting tumor proliferation by acetylating histone H3K9 on the TERT promoter." (PMID 39940762, 2025). "This identifies a tumor-specific approach to control TERT expression and thus inhibit tumor growth with limited toxicity." (PMID 40463649, 2025). "Currently, the only related product in clinical trials is the oncolytic adenovirus OBP-301, which exploits TERT promoter activity to achieve anti-tumor effects through virus replication." (PMID 39915447, 2025). "The tumor volumes were reduced by approximately half in the si-TERT groups compared to the NC groups, indicating that TERT silencing effectively suppresses tumorigenicity." (PMID 40688111, 2025). "TERT and ATRX-alterations are associated with metastatic PCPG and these tumours have an increased mutation load, and distinct transcriptional and telomeric features." (PMID 40097403, 2025). "A reduction in TERT + cells can serve as a quantitative and measurable indicator of the shift from “immune control of the tumor” to “tumor suppression of immunity”." (PMID 41417416, 2025). "PDTC is a RAS and TERT-driven neoplasia, with high prevalence rates of 35.57% and 44.83%, respectively." (PMID 40564998, 2025). "TERT promoter is used to control the highly tumor-specific expression of αCD3 and LIGHT, significantly reducing the systemic toxicity by minimizing off-target effects in healthy tissues." (PMID 41406950, 2025). "Univariate analyses also revealed a significantly higher likelihood of tumor relapse or tumor-related death among patients with PTCs whose cells showed TERT amplification concurring with other genetic alterations such as TPM, BRAF, or TPM + BRAF mutations." (PMID 40272676, 2025). "Tumors derived from si-TERT-treated cells were notably smaller compared to the control group (NC), with a significant reduction in tumor volume observed in both 143b and U2OS cell lines." (PMID 40688111, 2025). "The decreased expression of key proliferative markers such as Ki67 and TERT in the tumor tissues further corroborates the relationship between SNEX-associated genes and immune cell infiltration." (PMID 40688111, 2025). "Studies have shown that metabolic reprogramming increased the expression of the TERT oncogene through epigenetic changes such as histone acetylation, thereby promoting tumor cell proliferation." (PMID 39086383, 2024). "All TERT-altered cases had elevated TERT expression with the highest expression observed in the AFF4:TERT fusion tumour." (PMID 38978571, 2024).
tumor (continued). "It has also been observed that telomeres are shorter in tumor cells compared to adjacent hepatic cells or hepatocytes within cirrhotic parenchyma, despite elevated TERT expression in tumor cells." (PMID 38927059, 2024). "The alluvial plot shows the distribution and relationships between survival rate, tumor grade, TERT genetic profile, and adjuvant radiotherapy." (PMID 38893240, 2024). "Upon nuclear import, TERT can bind NF-κB and regulate the expression of NF-κB-dependent genes that are crucial for tumor progression." (PMID 39126110, 2024). "Non-invasive imaging determination of TERT reactivation can indicate the tumour’s malignancy and resistance to therapy." (PMID 38672647, 2024). "Some of them are tightly correlated to tumours, such as telomerase reverse transcriptase (TERT), a ribonucleoprotein polymerase that adds telomerase repeats TTAGG to maintain telomere ends." (PMID 38966428, 2024). "Much of what is known about TERT function is based on studies in cancer cells, in which it is often re‐activated and promotes tumor growth by enabling enzymatic activity of telomerase." (PMID 38475941, 2024). "Overexpressed TERT upregulates oncogenic signaling pathways, which are crucial in maintaining tumor immortality and contributing to tumor progression in BC, to maintain telomere integrity." (PMID 39001362, 2024). "A rare type of DHGTC was confirmed histopathologically in a patient with a TERT promoter variation based on a resected nodule exhibiting ≥5 mitoses per 2 mm2 and/or tumor necrosis." (PMID 39600648, 2024). "For example, in one study, researchers created a dual tumor-specific vector system using PEGylation and a telomerase reverse transcriptase (TERT) promoter for tumor therapy through systemic vector administration in mice." (PMID 39596526, 2024). "It should be noticed that the average level of TERT methylation is low in thyroid tissues, therefore we next defined hypermethylation in the tumor samples and obtained 33 of 531 (5.8%) TERT hypermethylated samples." (PMID 38313800, 2024). "Co-occurrence of BRAF V600E mutation and TERT mutations is linked with increased level of tumour aggressiveness in case of PTC as compared to BRAF and TERT mutations occurring alone." (PMID 39558949, 2024). "These include promoter mutations in TERT, which are independently predictive of DTC-related death and strongly associated with high tumor aggressiveness." (PMID 39600648, 2024). "Our multivariate model included age, sex, tumor localization, presence of edema, volumetric analyses and histopathological variables (WHO, TERT promotor mutation status, brain invasion)." (PMID 38581569, 2024). "Experiments utilizing mouse tumor models reveal that TERT-augmented tumor-active T cells retain robust antitumor responses." (PMID 39376566, 2024). "Meanwhile, few genes were uniquely expressed in TERT-altered tumours but included IRX3, SDK1 and TRIP13." (PMID 38978571, 2024).
tumor (continued). "In differentiated cells, the progressive silencing of TERT is involved in cell death, whereas in tumour cells, its activation plays a key role in tumour telomeres maintenance and in cell immortality." (PMID 39090361, 2024). "TERT and ATRX-alterations were associated with metastatic PCPG and these tumours had an increased mutation load, and distinct transcriptional and telomeric features." (PMID 38978571, 2024). "Molecularly, all tumor models exhibit common driver mutations in CTNNB1 and AXIN1, with TLCT models showing the characteristic TERT mutation, and some models progression-associated alterations in the NFE2L2 and NRAS genes." (PMID 39529166, 2024). "A correlation between IDH status, TERT mutations, MGMT methylation, and tumor location characteristics was also studied." (PMID 38893240, 2024). "According to one study, TERT promoter mutations were frequently recurrent in MLS (29/39; 74%) and were not linked to the phenotype (myxoid vs. round cell variation), tumor grade, tumor location, median age, or sex of the patients in the current MLS series." (PMID 39239547, 2024). "Although our data suggests that TERT is an important immune modulator in the tumor microenvironment, our methodology has two notable limitations." (PMID 39717106, 2024). "The fourth and final step allows the tumor cells to achieve immortality through telomerase reverse transcriptase promoter (TERT-p) or ALK alterations, which overcome replicative senescence through longer telomeres." (PMID 38247727, 2024). "Current guidelines stratify the patient groups at risk for PTC based on parameters that predict the recurrence of tumors, such as tumor size, ETE, LNM, and BRAF/TERT mutations." (PMID 38337788, 2024). "We conducted an analysis on the expression levels of the TERT and IL2RA genes in tumor microenvironment-associated cells within OS, using the TISCH database." (PMID 38431660, 2024). "We aimed to investigate the AF of BRAF V600E and TERT mutations in intermediate-to-high risk PTC and their association between tumor invasiveness, prognosis, and other mutations." (PMID 38607456, 2024). "TERT promoter hypermethylation and concordant overexpression was also observed in a single metastatic TERT wild type tumour (E171-M1)." (PMID 38978571, 2024). "The combination of TERT promoter mutations and BRAF p.V600E is expected to provide a strong genetic basis for tumor aggressiveness." (PMID 38667446, 2024). "This is one possible explanation for the short response in our patient who has co‐mutations identified in the initial tumour sample at diagnosis including NTRK1 over‐expression, TERT gain of function mutation and CDKN2A and CDKN2B loss." (PMID 39188081, 2024). "They used a doxycycline-inducible CRISPR interference system to knock down TERT expression in vivo early and late in tumor development." (PMID 39201386, 2024). "No RAS variants were detected in the 2 CMTC tumors, but 1 CMTC tumor presented with the coexistence of BRAF V600E and TERT promoter variants." (PMID 38758552, 2024). "Our study findings also revealed a noteworthy 2.5-fold upregulation of SLC5A8 and a 2.4-fold upregulation of SLC5A5 in the TERT-negative tumor as compared to the TERT-positive tumor." (PMID 38642578, 2024). "Post larotrectinib treatment, diagnostic I-123 whole body scan revealed unsuccessful RAI-uptake re-induction in the TERT-positive tumor, with a thyroid differentiation score (TDS) of −0.287." (PMID 38642578, 2024).
tumor (continued). "In 30 normal GTEx tissue types, the TERT-FL and TERT-β isoforms represented on average 17.7% and 58.5%, respectively, of the total TERT expression, while they represented 38.4% and 41.0%, respectively, in 33 tumor types in TCGA." (PMID 39802763, 2024). "They indicated that other genes, TERT and FGFR3, were most closely associated with tumour recurrence." (PMID 39768623, 2024). "TERT-positive patients are more likely to have older age, and have larger tumor size, more tumor invasiveness, and more advanced TNM stage, indicating a poor prognosis." (PMID 39235852, 2024). "Targeting GABPβ1L decreases TERT expression, leading to synergistic inhibition of tumor growth when combined with temozolomide." (PMID 39518074, 2024). "In an NSCLC mouse model, TERT promotes lung inflammation by influencing the expression of Ifng, Tnf, Il10, and PD-1, markers of inflammation, and tumor immunosuppression." (PMID 38278800, 2024). "Multivariate Cox regression analysis revealed that histological tumor grade, adjuvant radiotherapy, IDH status, and TERT-p status were significantly associated with overall survival." (PMID 38893240, 2024). "TERT directly regulates the transcription of numerous genes, including those involved in tumor growth, such as epidermal growth factor receptor (EGFR) and vascular endothelial growth factor (VEGF)." (PMID 39126110, 2024). "In a preclinical study, silencing TERT expression with antisense oligonucleotides led to the inhibition of tumor growth in cell lines and animal models." (PMID 39200261, 2024). "Research has shown that the hypermethylation region within the hTERT promoter is associated with upregulation of hTERT in cancers expressing hTERT, hence this region is called the TERT hypermethylation tumour region (THOR)." (PMID 38594465, 2024). "Clinically, TERT hypermethylation was correlated with tumor progression and unfavorable prognosis in several types of cancer." (PMID 38313800, 2024). "We further divided patients with PMME into high and low TERT methylation groups using the median TERT methylation level of tumor and normal samples from the PMME cohort." (PMID 38695555, 2024). "Current research indicates that in a 433 bp genomic region known as the TERT hypermethylated tumor region (THOR), located at the 52 CpG sites upstream of the TERT core promoter." (PMID 38594465, 2024). "Cancers have widespread transcriptional changes compared to non‐transformed healthy tissue, yet the influence of TERT on miRNA expression is not limited to neoplasms." (PMID 37041671, 2023). "Fifty percent (50%) of Bhigh/TERThigh patients were HPV-positive vs. ∼20% in the Bhigh/TERTlow group (odds ratio = 4.13; P = 0.002), consistent with the induction of TERT by the E6 protein expressed in HPV + HNSC tumor cells." (PMID 36909826, 2023). "Yet, within our discovery approach, we identified a consistent upregulation of DNA2 with higher TERT expression in several bulk tumor cohorts, potentially pointing to a role of TERT in DNA repair." (PMID 37418389, 2023). "Both binary and semi-quantitative approaches have found links between primary tumour BRAF and TERT promoter mutations and avidity in metastatic lesions." (PMID 37284971, 2023).